Y_RNA (Y RNA )
Gene: Miscellaneous RNA gene on chromosome 6 (134,283,092 to 134,283,193, forward strand). Ensembl gene ENSG00000201309.
Homologues: Orthologues: chimpanzee Y_RNA (99% identical), macaque Y_RNA (97% identical), guinea pig Y_RNA (88% identical). Paralogues in human: Y_RNA (90% identical), RNY3 (89% identical), Y_RNA (89% identical), RNY3P1 (88% identical), Y_RNA (88% identical), Y_RNA (87% identical), Y_RNA (86% identical), Y_RNA (85% identical), RNY3P14 (84% identical), RNY3P16 (84% identical), Y_RNA (84% identical), RNY3P11 (83% identical), and 97 more.